CRIM1 (cysteine rich transmembrane BMP regulator 1)
Diseases named in the same sentence as CRIM1 in open-access papers (continued):
Sharing a sentence is not in itself a finding about the gene and the disease.
acute lymphoblastic leukemia (2 papers, 2021 to 2022). Leukemia with an acute onset, characterized by the presence of lymphoblasts in the bone marrow and the peripheral blood. "Besides, a CRIM1 variant has been associated with neutropenia during pediatric acute lymphoblastic leukemia, suggesting its possible effects on neutrophil activity, which is important for mastitis pathogenesis." (PMID 36336691, 2022). "Despite the impact of homozygous CRIM1 on thiopurine toxicity, several patients with wild-type NUDT15, TPMT, and CRIM1 experience thiopurine toxicity, therapeutic failure, and relapse of acute lymphoblastic leukemia (ALL)." (PMID 33958640, 2021).
asthma (2 papers, 2013 to 2023). "For instance, novel IgE-related genes (CRIM1, ZNF71, TLN1, and SYNPO2) were uncovered by the only GWAS of IgE in asthma patients." (PMID 37761964, 2023). "Instead, this study identified additional candidate genes (CRIM1, ZNF71, TLN1, SYNPO2, etc.)for total serum IgE levels in asthma patients." (PMID 23967269, 2013).
coloboma (2 papers, 2021 to 2025). An abnormality in which a part of a structure in one or both eyes is missing. "The interaction between Crim1 and integrins at the lateral surfaces of LE cells provides a mechanism for cell adhesion between LE cells and may be relevant to eye defects, including coloboma." (PMID 40114969, 2025).
colorectal cancer (2 papers, 2022). A primary or metastatic malignant neoplasm that affects the colon or rectum. "The targeting of miR-199b-3p to cysteine-rich transmembrane BMP regulator 1 (CRIM1) inhibits Wnt/β-catenin signaling and reverses resistance to cetuximab in colorectal cancer." (PMID 35684449, 2022).
congenital cataracts (2 papers, 2016 to 2023). "We identified 18 HUB genes, among which four core genes, C1qa, C1qb, C1qc, and Cd74, were closely related to congenital cataracts induced by Crim1 mutation." (PMID 36586009, 2023). "In our study, we used mature bioinformatics tools to screen potential genes in congenital cataracts induced by Crim1 mutations." (PMID 36586009, 2023). "In mutant and spontaneous null mouse models, Crim1 is one of the key genes causing congenital cataracts." (PMID 36586009, 2023). "Therefore, knowledge on the mechanism of congenital cataracts induced by Crim1 mutations can further predict the occurrence and development of congenital cataracts and provide some guidance for early identification and intervention treatment of congenital cataracts." (PMID 36586009, 2023). "In conclusion, through comprehensive biological analysis of the GSE62561 gene expression profile, a total of 750 DEGs were identified, of which C1qa, C1qb, C1qc, and Cd74 may be related to the occurrence and development of congenital cataracts caused by Crim1 mutations." (PMID 36586009, 2023). "This study reveals the molecular pathogenesis of congenital cataracts induced by Crim1, and this information is expected to facilitate clinical genetic testing, molecular diagnosis, prognosis, and individualized chemotherapy for congenital cataracts (CC)." (PMID 36586009, 2023).
breast tumors (1 paper, 2015). "Candidates that exhibited the strongest association with breast tumors were regions from the longest introns of RFX2, EPAS1, RBMS1, ZEB2, and the three different introns of CRIM1." (PMID 25798919, 2015).
congenital heart disease (1 paper, 2024). A heart disease that is present at birth. "Recently, an integrated multi-omics study was performed to characterize the congenital heart and found congenital heart disease (CHD)-specific cell states in cardiomyocytes, which provided evidence of insulin resistance and induced gene expression by FOXO and CRIM1." (PMID 38885281, 2024).
diabetes (1 paper, 2019). "A SEM was fitted to compare the effect sizes of the SNP rs4016189, that is near CRIM1, with known risk factors for kidney disease, blood pressure, and diabetes." (PMID 31040861, 2019).
glaucoma (1 paper, 2025). Increased pressure in the eyeball due to obstruction of the outflow of aqueous humor. "We present three patients with heterozygous deletions and truncating variants predicted to result in haploinsufficiency for CRIM1 as further evidence for the role of this gene in eye defects, including retinal coloboma, optic pallor, and glaucoma." (PMID 40114969, 2025).
hypertrophy (1 paper, 2022). Hypertrophy is the increase in the volume of an organ or tissue due to the enlargement of its component cells. "Overexpression of Crim1 by Ad-Crim1 transfection significantly attenuated the effects of Ang II on ventricular cell hypertrophy." (PMID 36311192, 2022).
iris coloboma (1 paper, 2016). "At E18.5, one compound heterozygous P0-3.9-GFPCre;Crim1flox/+;Itgb1flox/+ mouse out of four displayed iris coloboma similar to that seen in human CRIM1 haploinsufficiency." (PMID 26681494, 2016). "Interestingly, Crim1null and Itgb1flox compound heterozygotes displayed iris coloboma and cataract, confirming that Crim1 and Itgb1 genetically interact." (PMID 26681494, 2016).
liver fibrosis (1 paper, 2025). "CRIM1 expression was upregulated in human liver fibrosis and BDL-induced mouse liver fibrosis." (PMID 40943308, 2025).
melanoma (1 paper, 2024). A malignant, usually aggressive tumor composed of atypical, neoplastic melanocytes. "For example, YAP-mediated melanoma cell invasion was found to require the YAP-dependent induction of AXL, CRIM1, and CYR61." (PMID 38473214, 2024). "We also found that although some established YAP/TAZ target genes (CRIM1, F3, ANKRD1) correlated strongly with CTGF and CYR61 expression in human melanoma, others did not (WWC1, FOSL1, FSTL3)." (PMID 38473214, 2024).
renal carcinoma (1 paper, 2022). A carcinoma arising from the epithelium of the renal parenchyma or the renal pelvis. "Additionally, Ogasawara’s group found that CRIM1 plays a suppression role in the migration and invasion of renal carcinoma cells via regulating EMT-related factors." (PMID 35090460, 2022).
Varicose veins (1 paper, 2024). Enlarged and tortuous veins. "A comprehensive analysis indicated that KRTAP5-AS1, PLEKHA5, CBWD1, and CRIM1 might be potential drug targets for varicose veins." (PMID 38818040, 2024).
Ventricular arrhythmia (1 paper, 2022). "We found that Crim1 inhibits the reduction of Kv4.2 expression and Ito current density induced by Ang II, indicating that Crim1 may be a regulator of ventricular arrhythmia in pathological hypertrophic hearts." (PMID 36311192, 2022). "Crim1 could have a role in the development of ventricular arrhythmia in hypertrophic hearts." (PMID 36311192, 2022).
cancer (13 papers, 2012 to 2023). A tumor composed of atypical neoplastic, often pleomorphic cells that invade other tissues. "CRIM1 is a potential risk factor of cancer that regulates the migration of cancer cells." (PMID 31213036, 2019). "These literatures signposted the anti-cancer effect of CRIM1." (PMID 35090460, 2022). "The rate of CRIM1 positivity in normal breast tissues was 58.42%, relative to 39.62% in carcinoma." (PMID 35600360, 2022). "This led us to speculate that once a PC cell arrives to the bone, the microenvironment rich in Wnt signaling facilitates molecular changes in cancer cells, including the upregulation of CRIM1 expression." (PMID 26545120, 2015). "Elevated levels of CRIM1 subsequently may promote the formation and stabilization of cadherin-dependent adhesion complexes, which may mediate cell-cell physical contact between bone and cancer cells." (PMID 26545120, 2015). "CCL2, CRIM1, COL1A1, 6A1, 6A2 participate in cell migration, invasion, or EMT and ABCG2, ALDH1A1, NES are cancer stem‐cell markers." (PMID 36305167, 2022). "Thus, CRIM1 may have therapeutic or biomarker potential against cancer." (PMID 35600360, 2022). "Their host genes had been described in individual studies with regard to their roles in either PCa progression (e.g., CRIM1, NEAT1, and STIL) or other cancers (e.g., LPP and RHOBTB3)." (PMID 33105568, 2020). "Combined with the results of previous studies implicating the indirect interaction of the cytoplasmic domain of CRIM1 with β-catenin during nervous system development, it may be inferred that CRIM may impede Wnt signaling by binding to β-catenin during cancer progression." (PMID 35090460, 2022).
tumor (6 papers, 2015 to 2025). "Consistent with the observed down-regulation of RFX2, ZEB2, and CRIM1 regions using qRT-PCR, in-situ hybridizations with probes corresponding to these genomic loci clearly reveal that these loci are down-regulated in tumor epithelium." (PMID 25798919, 2015). "For example, 19 tightly clustered regions down-regulated in the tumor samples are located within the introns of the CRIM1 gene." (PMID 25798919, 2015). "However, the authors revealed that under-expression of CRIM-1 increases tumor invasion and epithelial-mesenchymal transition by reducing E-cadherin expression and increasing claudin-1 and MMP-2 and -9 expression." (PMID 38188015, 2023). "The correlation of the expression of CRIM1 with tumor immune infiltration was explored via TIMER." (PMID 35600360, 2022). "Notably, CRIM1 expression was positively linked to the level of infiltration by CD8+ T-cells, endothelial cells, and neutrophils, and negatively linked to NK, B-cells, CD4+ T-cells, tumor purity, macrophage M1, and Tregs." (PMID 35600360, 2022). "In the SWI/SNF-mutant cohort, a seven-gene signature comprising CRIM1 (angiogenesis), VEGFC (lymphangiogenesis), BMP7 (tumor microenvironment regulation), NR1D2 (immune modulation), BMPR1B (tumor proliferation), CR2 (B-cell activation), and TAPBPL (antigen presentation) was ultimately retained." (PMID 41438758, 2025). "The authors demonstrated that decreased expression of CRIM-1 does not impact tumor growth or proliferation." (PMID 38188015, 2023). "Our study exhibited that overexpressing CRIM1 effectively enhanced the anti-tumor effects of CTx on the cell proliferation, apoptosis, migration, and invasion of CRC-CTxR cells, hinting that CRIM1 OE could reverse acquired resistance of CRC-CTxR cells to CTx." (PMID 35090460, 2022). "Collectively, our data suggest that silencing miR-199b-3p could enhance the anti-tumor effects of CTx on CTx-resistant CRC in vitro and in vivo by activating Wnt/β-catenin signaling via the down-regulation of CRIM1." (PMID 35090460, 2022).
heart disease (1 paper, 2016). "Moreover, whether or not abnormal CRIM1 expression plays a role in congenital human heart disease will be an important topic for future investigations." (PMID 26821812, 2016).
renal disease (1 paper, 2019). "Two of these loci, single nucleotide polymorphisms (SNPs) rs443816 located in the gene encoding UGT2B11 and rs4016189 located in the gene encoding CRIM1, were also significantly associated with the renal disease phenotype in an independently sampled cohort." (PMID 31040861, 2019). "It is therefore tempting to speculate that the renal disease associated variants modify CRIM1 expression in such a way as to affect the developing kidney and lead, possibly in conjunction with added environmental factor(s), to the renal disease susceptibility phenotype in the Tiwi." (PMID 31040861, 2019).
CRIM1 also shares sentences with these, for which no sentence is quoted: neutropenia (2 papers); non-small cell lung carcinoma (2); airway hyperresponsiveness (1); Alzheimer disease (1); bipolar disorder (1); bladder cancer (1); bone tumors (1); Charcot-Marie-Tooth disease (1); Cirrhosis (1); dengue (1); endothelial dysfunction (1); hypoplastic left heart syndrome (1); infection (1); infiltrative ductal breast carcinoma (1); infiltrative lobular breast carcinoma (1); left ventricular hypertrophy (1); mastitis (1); medullary breast carcinoma (1); medullary carcinoma (1); myopia (1); neurodegenerative disease (1); optic atrophy (1); Optic disc pallor (1); prostate carcinoma (1); pterygium (1); reproductive system diseases (1); Retinal coloboma (1); schizophrenia (1); triple-negative breast carcinoma (1).